TNIP1 (TNFAIP3 interacting protein 1)
Description:
Inhibits NF-kappa-B activation and TNF-induced NF-kappa-B-dependent gene expression by regulating TAX1BP1 and A20/TNFAIP3-mediated deubiquitination of IKBKG; proposed to link A20/TNFAIP3 to ubiquitinated IKBKG. Involved in regulation of EGF-induced ERK1/ERK2 signaling pathway; blocks MAPK3/MAPK1 nuclear translocation and MAPK1-dependent transcription. Increases cell surface CD4(T4) antigen expression. Involved in the anti-inflammatory response of macrophages and positively regulates TLR-induced activation of CEBPB. Involved in the prevention of autoimmunity; this function implicates binding to polyubiquitin. Involved in leukocyte integrin activation during inflammation; this function is mediated by association with SELPLG and dependent on phosphorylation by SRC-family kinases. Interacts with HIV-1 matrix protein and is packaged into virions and overexpression can inhibit viral replication. May regulate matrix nuclear localization, both nuclear import of PIC (Preintegration complex) and export of GAG polyprotein and viral genomic RNA during virion production. In case of infection, promotes association of IKBKG with Shigella flexneri E3 ubiquitin-protein ligase ipah9.8 p which in turn promotes polyubiquitination of IKBKG leading to its proteasome-dependent degradation and thus is perturbing NF-kappa-B activation during bacterial infection.
Synonyms: ABIN-1; Naf1; VAN; KIAA0113; nip40-1
Tractability: PROTAC: ubiquitination databases record sites on it; its protein half-life has been measured.
Gene: Protein-coding gene on chromosome 5 (151,029,939 to 151,093,577, reverse strand). Ensembl gene ENSG00000145901.
Subcellular location: Cytoplasm; Nucleus
Subcellular location (Human Protein Atlas): Nucleoplasm; Cytosol
Pathways (Reactome):
Metabolism of proteins: Ovarian tumor domain proteases
Gene Ontology:
Molecular function: identical protein binding; mitogen-activated protein kinase binding; protein binding
Biological process: glycoprotein biosynthetic process; leukocyte cell-cell adhesion; negative regulation of canonical NF-kappaB signal transduction; negative regulation of ERK1 and ERK2 cascade; positive regulation of protein deubiquitination; cellular response to lipopolysaccharide; defense response; MyD88-dependent toll-like receptor signaling pathway; negative regulation of viral genome replication; positive regulation of inflammatory response; positive regulation of transcription by RNA polymerase II; regulation of transcription by RNA polymerase II; translation
Cellular component: cytosol; nucleoplasm; cytoplasm; nucleus
Genetic constraint (gnomAD): Loss-of-function variants: 22 observed, 84.32 expected, observed/expected ratio (o/e) 0.26, 90% interval 0.19 to 0.37. The upper end of that interval is the gene's LOEUF score, 0.37, which puts it in group 1 of 6, group 1 being the genes least tolerant of losing a copy. Missense variants: 705 observed, 803.77 expected, observed/expected ratio (o/e) 0.88, 90% interval 0.82 to 0.93. Synonymous variants: 289 observed, 304.89 expected, observed/expected ratio (o/e) 0.95, 90% interval 0.86 to 1.04.
Homologues: Orthologues: chimpanzee TNIP1 (97% identical), macaque TNIP1 (92% identical), pig TNIP1 (85% identical), dog TNIP1 (84% identical), mouse Tnip1 (83% identical), guinea pig TNIP1 (83% identical), rat Tnip1 (82% identical), tropical clawed frog tnip1 (49% identical), zebrafish tnip1 (45% identical). Paralogues in human: TNIP3 (19% identical), TNIP2 (13% identical).
Diseases named in the same sentence as TNIP1 in open-access papers:
TNIP1 is named in the same sentence as 100 diseases in open-access papers, as found by Europe PMC text mining. Sharing a sentence is not in itself a finding about the gene and the disease. The quoted sentences say what the papers report.
psoriasis (40 papers, 2011 to 2025). An autoimmune condition characterized by red, well-delineated plaques with silvery scales that are usually on the extensor surfaces and scalp. "These experimental findings bolster the results of genome-wide association studies (GWAS) linking TNIP1 with several hyperinflammatory and autoimmune disorders, e.g., psoriasis, psoriatic arthritis, and systemic lupus erythematosus (SLE), as we have reviewed." (PMID 40149990, 2025). "Previous studies have indicated that mutations in TNIP1 are associated with psoriasis, rheumatoid arthritis, systemic lupus erythematosus, and leukemia and lymphoma." (PMID 37781923, 2023). "Loss of TNIP1 in keratinocytes leads to deregulation of IL-17-induced gene expression and increased chemokine production in vitro and psoriasis-like inflammation in vivo." (PMID 36699407, 2022). "Further investigation indicated TNIP1/ABIN1 deficiency in keratinocytes was sufficient to promote psoriasis inflammation, which disturbed IL-17-induced gene expression, and exaggerated chemokine and cytokine production." (PMID 35075118, 2022). "Global deletion of TNIP1/ABIN1 caused mice susceptible to the development psoriasis-like dermatitis induced by IMQ." (PMID 35075118, 2022). "After that, numerous studies on the association of single nucleotide polymorphisms in TNFAIP3 and TNIP1 with the risk of psoriasis have conducted." (PMID 32398022, 2020). "Our findings indicated that rs610604 in TNFAIP3 and rs17728338 in TNIP1 gene polymorphisms were associated with psoriasis susceptibility." (PMID 32398022, 2020). "Tumour Necrosis Factor Alpha-Induced Protein 3 (TNFAIP3) and TNFAIP3 Interacting Protein 1 (TNIP1) are among them, and they were first discovered to be associated with psoriasis in 2009." (PMID 32398022, 2020). "Genome-wide association surveys have revealed that TNFAIP3 and TNIP1 were key biomarkers for psoriasis." (PMID 32398022, 2020). "Keratinocyte TNIP1 deficiency sensitizes cells to PAMPs and DAMPs promoting hyperresponsive expression and secretion of cytokine markers (e.g., IL-8 and IL-6) relevant to cases of chronic inflammation, like psoriasis, where TNIP1 deficiency has been reported." (PMID 32377162, 2020). "To date, this is the first comprehensive study on the correlation between TNFAIP3 and TNIP1 polymorphisms and psoriasis vulnerability." (PMID 32398022, 2020). "The results of our meta-analysis suggested that G allele of rs610604 polymorphisms in TNFAIP3 and A allele of rs17728338 polymorphisms in TNIP1 were considered to have an increased risk for psoriasis." (PMID 32398022, 2020). "Here, we intended to conduct a survey on the association between TNFAIP3 and TNIP1 gene polymorphisms and psoriasis risk." (PMID 32398022, 2020). "TNIP1, encoding A20 binding and inhibitor of NF-κB-1 (ABIN1), is also associated with susceptibility to psoriasis." (PMID 31156649, 2019). "Previous studies have shown genetic variants in TNIP1 associated with various autoimmune conditions including psoriasis, and systemic lupus erythematous." (PMID 27508393, 2016). "According to genome-wide association studies (GWAS), the TNIP1 gene, which encodes the TNF-α–induced protein 3-interacting protein 1 (TNIP1), is strongly linked to the susceptibility of psoriasis." (PMID 26046540, 2015). "A polymorphism of rs17728338 near TNIP1 was first reported to be associated with psoriasis in Americans from European ancestry and subsequently confirmed in other Caucasian populations with PsA." (PMID 24788730, 2014). "Additionally, the rs7708392 SNP in the TNIP1 gene was associated with psoriasis, suggesting a role in modulating NF-κB activity and immune responses." (PMID 37569685, 2023). "Similar with TNFAIP3, more than 3 genome-wide association studies (GWAS) indicated that TNIP1 had been implicated in numerous inflammatory disease, including psoriasis, psoriatic arthritis, systemic lupus erythematosus (SLE), systemic sclerosis (SSC), rheumatoid arthritis (RA)." (PMID 32398022, 2020).
psoriasis (continued). "Considering that study sample sizes were small and the statistical effect was limited of an individual study, this meta-analysis is meant to provide the most comprehensive and precise evaluation on the association of TNFAIP3 and TNIP1 polymorphisms with psoriasis vulnerability." (PMID 32398022, 2020). "Parallel to genetic studies, expression microarray experiments have implicated TNIP1 in disease pathogenesis although seemingly paradoxically as its increased transcription was reported for the inflammatory diseases of rheumatoid arthritis and psoriasis." (PMID 30402506, 2018). "Besides psoriasis, the TNIP1 and TNFAIP3 gene have been associated with systemic lupus erythematosus (SLE)." (PMID 26046540, 2015). "Hence, downregulated TNIP1 expression in the skin increases the susceptibility to experimental psoriasis in mice." (PMID 26046540, 2015). "Other autoimmune diseases such as SLE, RA and psoriasis, which had been found with association with TNIP1 polymorphisms, may share autoimmune features and mechanism with VKH syndrome and Behçet’s disease (BD)." (PMID 24788730, 2014). "However, it is currently unknown whether reduced TNIP1 epidermal expression in psoriasis is caused by transcriptional or post-transcriptional regulation." (PMID 26046540, 2015). "A20 and its cofactor ABIN1 (TNIP1) form a widely recognized core of ubiquitin pathway regulation in psoriasis." (PMID 41362701, 2025). "Concerning miRNAs, it has been identified that hsa-miR-19a-3p has great potential to become a biomarker for psoriasis because it binds to the mRNA of seven genes (CAST, TSC1, SPATA2, ERAP1, TNIP1, ERBB3 and SDC4) thatare associated with psoriasis." (PMID 40725409, 2025). "Genetic variants within the major histocompatibility complex (MHC) and the TNIP1 and IL12B psoriasis susceptibility loci were associated with severe disease at genome-wide significance (P < 5.0 × 10-8)." (PMID 41408349, 2025). "As such, knockout of TNIP1 in mice greatly increases their sensitivity to topically applied imiquimod in developing psoriasis-like skin symptoms." (PMID 37569318, 2023). "TNIP1 SNPs have been reported in several GWAS publications linking it to inflammatory diseases like psoriasis, systemic lupus erythematosus (SLE), psoriatic arthritis, and systemic sclerosis." (PMID 37569318, 2023). "The genes associated with psoriasis that encode regulators of the NF-kB pathway include TNFAIP3, TNFRSF1B, TNIP1, TRAF1IP2, and NF-κ-BIA." (PMID 37569685, 2023). "Tumor necrosis factor alpha induced protein 3 (TNFAIP3/A20) and TNFAIP3 interacting protein 1 (TNIP1) have been accepted as the related candidate genes for psoriasis." (PMID 33981308, 2021). "Consistently, many psoriasis susceptibility genes encode the TRAF6 signaling players, such as ACT1 (TRAF3IP2), A20 (TNFAIP3), ABIN1 (TNIP1), IL-36Ra (IL36RN), IkappaBzeta (NFKBIZ), and CARD14." (PMID 31156649, 2019). "To identify the most critical splicing changes in psoriasis, we conducted a splicing conservation analysis to reveal the splicing changes common to both the Tnip1 KO mouse model dataset and the human psoriasis dataset." (PMID 29515135, 2018). "In these mice, tissue with reduced TNIP1 had a significantly higher overall psoriasis disease score, as compared to wild-type IMQ treated." (PMID 30402506, 2018). "The 18 conserved ES events were significantly conserved in the Tnip1 KO mouse model dataset and the human psoriasis dataset, indicating the key spliced genes in psoriasis." (PMID 29515135, 2018). "In the Tnip1 KO mouse model dataset, 64 splicing events have more inclusion of the variable exons in psoriasis, while 117 splicing events have less inclusion of the variable exons in psoriasis." (PMID 29515135, 2018). "From MSA analysis, we detected 18 conserved genes sharing a common splicing pattern between the Tnip1 KO mouse model dataset and the human psoriasis dataset, several of which can be potentially critical in psoriasis." (PMID 29515135, 2018).
psoriasis (continued). "The large-scale DAS changes in the Tnip1 KO samples compared with wild-types provided a feasible discovery of the key splicing features in psoriasis." (PMID 29515135, 2018). "As presented below, TNIP1 is an oft-cited gene in GWAS studies with SNPs in certain populations suffering from systemic lupus erythematosus, psoriasis, and systemic sclerosis." (PMID 30402506, 2018). "Other genes associated with psoriasis are genes encoding zinc-finger protein 313 (ZNF313), TNFAIP3 interacting protein 1 (TNIP1), and TNF-α-induced protein 3 (TNFAIP3) within the nuclear factor- (NF-) κB pathway." (PMID 29619128, 2018). "Increasing evidence indicates that genetic mutations in genes such as TNFAIP3, TNIP1, NFKBIA, TRAF3IP2, and CARD14 result in an impaired negative regulation of NF‐κB proinflammatory activity leading to psoriasis." (PMID 28377495, 2017). "Intradermal injection of TNIP1 shRNA in BALB/c mice led to exaggerated psoriatic conditions in imiquimod (IMQ)-induced psoriasis-like dermatitis." (PMID 26046540, 2015). "Our study revealed that mice with decreased TNIP1 were more vulnerable to IMQ-induced psoriasis-like dermatitis." (PMID 26046540, 2015). "Nevertheless, we confirmed that TNIP1 downregulation in mice skin led to exaggerated psoriasis-like dermatitis." (PMID 26046540, 2015). "We further identified previously unreported pleiotropic alleles with opposing effects on atopic dermatitis and psoriasis risk in PRKRA and ANXA6/TNIP1." (PMID 25574825, 2015). "Based on previous studies suggesting a role for TNIP1 in modulating cancer cell growth, we investigated its role in keratinocyte proliferation, which is clearly abnormal in psoriasis." (PMID 26046540, 2015). "SNPs in the TNFAIP3 gene, but also in other immune-regulatory genes including HLA-C, TNIP1/ABIN-1 and IL-23A have been associated to psoriasis and polymorphisms in the TNFAIP3 gene correlate to responsiveness to TNFα blockers in psoriasis patients." (PMID 26124703, 2015). "Key genetic loci such as HLA-C, TNIP1, IL12B, and IL23R are linked to psoriasis." (PMID 40557155, 2025). "In addition, CARD14E138A-3xFLAG pulldowns contained ABIN1 (TNIP1) and A20 (TNFAIP3), the ubiquitin binding proteins which are encoded by genes that reside in loci identified through psoriasis GWAS." (PMID 39145956, 2024). "Furthermore, the inhibitory effect of TNIP1/ABIN1 on psoriasis is mainly attributed to the suppression of inflammatory responses in keratinocytes rather than inhibiting keratinocyte proliferation." (PMID 35075118, 2022). "In addition, the NF-κB inhibitors TNFAIP3 (TNF-α induced protein 3, encoding A20) and TNIP1 (TNFAIP3-interacting protein 1, encoding ABIN1) have been identified as susceptibility loci for psoriasis and keratinocyte-associated genes." (PMID 35075118, 2022). "To identify the splicing features in psoriasis, we further evaluated whether the common splicing events were conserved in the same isoform between the Tnip1 KO mouse model dataset and the human psoriasis dataset." (PMID 29515135, 2018). "Moreover, genome-wide association studies identified polymorphisms in TNIP1, the gene encoding ABIN1, which predispose to lupus, psoriasis, and other autoimmune disorders in eight human populations." (PMID 27807192, 2016). "To investigate whether downregulation of TNIP1 expression could increase the severity of psoriasis, we used a widely accepted IMQ-induced psoriasis-like mice model, which is clinically and pathologically similar of human psoriasis." (PMID 26046540, 2015). "At least 36 different loci have been identified as susceptibility loci of psoriasis by GWAS, including the TNIP1 gene, which encodes TNF-α–induced protein 3-interacting protein 1 (TNIP1), as well as the tumor necrosis factor α-induced protein 3 (TNFAIP3) gene, which encodes protein A20." (PMID 26046540, 2015).
psoriasis (continued). "Psoriatic skin displayed a 1.47-fold increase in the mRNA level of TNIP1, when compared with uninvolved skin, suggesting that TNIP1 may have a role in the pathogenesis of psoriasis." (PMID 26046540, 2015). "The aim of this study was to determine the potential role of TNIP1 in psoriasis." (PMID 26046540, 2015). "However, to clarify the mechanism of TNIP1 in the pathogenesis of psoriasis, it is necessary to extensively explore the functions of TNIP1 in vivo." (PMID 26046540, 2015). "Since psoriasis is characterized by excessive epidermal growth, we postulated whether TNIP1 could affect the proliferation of keratinocytes." (PMID 26046540, 2015). "In our study, TNIP1 expression decreased in specimens of epidermis affected by psoriasis." (PMID 26046540, 2015). "Recently, a genome-wide scan study in 1,409 psoriasis cases and 1,436 controls revealed associations between three genes of the IL-23 pathway (IL23A, IL23R and IL12B), two genes of nuclear factor-κB (NF-κB) pathway (TNIP1 and TNFAIP3) and psoriasis." (PMID 21555979, 2011). "Our previous study demonstrated that the TT genotype at rs10036748 in TNIP1 is associated with the PASI 75 and PASI 90 response to MTX in psoriasis patients, whichis related to MTX-inhibited NF-κB activation, and the variants of TNIP1 might correlate with the activation of NF-κB." (PMID 35956194, 2022). "Seven of these have previously been reported for psoriasis (MHC, TRAF3IP2, IL12B, IL23R, IL23A-STAT2, TNIP1, TYK2)." (PMID 25651891, 2015). "Thus, TNIP1 may be a potential therapeutic target for psoriasis." (PMID 26046540, 2015). "The most highly significant variant at 5q33.1 (rs17728338) shows opposing effects on AD and psoriasis (MNM p = 3.96 × 10−38) and lies 2 kb upstream of ANXA6 (MIM 114070) and 8 kb downstream of TNIP1 (MIM 607714)." (PMID 25574825, 2015). "Our data showed that TNIP1 played a role in modulating the proliferation of human keratinocytes and exaggerated IMQ-induced psoriasis-like dermatitis in mice." (PMID 26046540, 2015). "Using keratinocyte-specific TNIP1 knockout mice, these investigators demonstrated that keratinocyte-initiated immune signaling, through the IMQ-induced expression of numerous cytokines, antimicrobial peptides, and chemokines, can induce psoriasis-like disease." (PMID 30402506, 2018). "When taken together with genes (that is, TNIP1, TNFAIP3 and NFKBIA) mapping to known psoriasis loci that are well-appreciated as components of NF-κB signalling, our results further implicate this pathway in the pathophysiology of psoriasis." (PMID 28537254, 2017). "Two of the loci displaying opposing effects (ANXA6/TNIP1 and PRKRA) have not previously been reported in association with psoriasis and/or AD." (PMID 25574825, 2015). "In addition, rs610604 (TNFAIP3) and rs17728338 (TNIP1), but not rs2066808 (IL23R) and rs397211 (IL1RN), were associated with psoriasis in a case-control study." (PMID 24069534, 2013). "Subdomains within the TNIP1 protein as well as how they interact with ubiquitin have not only been mapped but inflammatory cell- and tissue-specific consequences subsequent to their defective function are being recognized and related to human disease states such as lupus, scleroderma, and psoriasis." (PMID 30402506, 2018). "Over the last decade, TNIP1 has been reported among the highest scoring non-MHC genes across multiple genome-wide association studies (GWAS), spanning multiple populations and diseases including psoriatic arthritis, systemic sclerosis, systemic lupus erythematosus, and psoriasis." (PMID 30402506, 2018).